IL2 (interleukin 2)
Diseases named in the same sentence as IL2 in open-access papers (continued):
Sharing a sentence is not in itself a finding about the gene and the disease.
tumor (continued). "However, in the TME, excessive IL-2 acts on CD8+T cells to promote their exhaustion in the later stages of continuous tumor growth." (PMID 37106742, 2023). "In summary, IL2-7NP2-TNFmut showed encouraging tumor-homing properties in lesions expressing cell membrane-bound FAP, a target that has been extensively validated by nuclear medicine procedures as an excellent accessible marker of various types of solid malignancies." (PMID 37092450, 2023). "Recent preclinical models demonstrate that IL-2/IL-2R agonists could enhance anti-tumor immune responses and reduce tumor growth." (PMID 37516849, 2023). "Indeed, CD8+T cells derived from tumors and tumor‐draining lymph nodes (TdLN) had a higher frequency of Ki‐67 expression in CT26‐bearing mice with FPC2‐IG‐IL‐2 injection compared to those that received PBS, FPC2‐IG, and free IL‐2." (PMID 36684086, 2023). "Cytokines such as IFNγ and IL-2 contribute to the anti-tumor effect of PD-1 blockade." (PMID 37189417, 2023). "In addition, many studies showed that Tregs in tumors can inhibit the proliferation of autologous CD4 and CD8 T cells [++25] and that the frequency of Tregs is negatively correlated with the expression of interferon (IFN)-γ and IL-2 in tumor tissues." (PMID 36755298, 2023). "We further investigated the anti-tumor effects of PC combined with IL-2 and PD-1 blockade." (PMID 37932447, 2023). "Local intratumoral injection of IL-2 after radiotherapy not only shrunk the irradiated tumor, but also inhibited distant metastasis development located outside the radiotherapy field in a Balb/c mouse model of simultaneous subcutaneous tumor and liver metastasis of the colon." (PMID 38006049, 2023). "Additionally, IL-2 encourages DC migration to lymph nodes, fostering T cell activation and instigating anti-tumor immune responses." (PMID 37516849, 2023). "In addition, a MARCH5 inhibitor potently improved the efficacy of immunotherapy triggered by PD-1 blockade and IL-2 in mouse tumor models." (PMID 37932447, 2023). "Other protumorigenic cytokines, such as GROα/β/γ, IL-8, and IL-6, are known to be secreted by cancer and stromal cells, whereas IL-2 and IL-3 are secreted from activated T cells to regulate the activity and maturation of immune cells to be able to eliminate tumor cells." (PMID 37759302, 2023). "The aim of our current study was to investigate the efficacy of combined Il-12 and Il-2 gene transfer in the mouse colorectal carcinoma tumour model, which is considered an immunologically “hot “ tumour with many expressed neoantigens and high immune cell infiltration." (PMID 37629081, 2023). "Interestingly, the Evans blue staining results revealed a reduction in vascular leakage in tumor-bearing mice treated with the combination of IL-2 and CU06-1004." (PMID 37711172, 2023). "Of note, the human IL-2 in NOG-IL2 mice may activate tumor-resident T cells in transplanted tumor pieces and reduce the engraftment rate of PDXs in NOG-IL2 compared to NOG mice." (PMID 37296949, 2023). "ASPS could increase the levels of IL-2 and IL-12 in the serum of S180, H22, and U14 tumor-bearing mice." (PMID 37959774, 2023). "Moreover, IL-2 has been shown to promote the growth and survival of specific tumor cells, and studies have demonstrated that IL-2R is involved in the angiogenesis or growth of new blood vessels in tumors." (PMID 37516849, 2023). "However, the present study reveals that CAP treatment enhances the expression of PD-1 and PD-L1 in T cells and tumor cells, respectively, but reduces the expression of T cell cytokines (IFNγ, GZMB, and IL-2) that are associated with CTL functions and activity." (PMID 37189453, 2023). "Thus, in the subcutaneous tumor model, only the level of IL‐2 showed significant differences between CAR‐T/NanoSwitch and CAR‐T/FreeSwitch group." (PMID 36755195, 2023). "However, in the late stage of tumor, IL-2 induced CD8+ T cell exhaustion in the tumor microenvironment by activating STAT5-5-HTP-AhR pathway." (PMID 37355637, 2023).
tumor (continued). "Furthermore, in the tumor microenvironment, Treg-dependent regulation of IL-2 was demonstrated to be critical for the acquisition of cytotoxic features by tumor-infiltrating CD4+ T cells." (PMID 37161048, 2023). "GSEA results suggest that high CHI3L1 expression is associated with biological processes involved in cytokine production (IL-2 and IL-6), mTORC1 and complement signaling, interferon-γ response, and inflammatory response, leading to an immunosuppressive effect in the tumor microenvironment." (PMID 37185706, 2023). "Low-dose paclitaxel could remodel the immunosuppressive TME and increase tumor immunogenicity to facilitate the immune activation induced by IL-2." (PMID 37497002, 2023). "The fact that the PI3K pathway is activated universally in T cells in response to IL-2 involvement may explain why IL-2 secreted by CD4+ T cells at the tumor site induces CXCR3 expression in various T- cell subsets." (PMID 38104126, 2023). "Similarly, IL-2 impacts macrophages’ functionality, promoting their differentiation into the M1 phenotype, known for their anti-tumor and potent tumoricidal activities." (PMID 37516849, 2023). "Indeed, our PD-1–laIL-2 specifically delivers IL-2 to exhausted tumor-specific T cells marked by high PD-1 and TIM3 expression and expands them with enhanced antitumor polyfunctionality, as indicated by high expression of IFN-γ and CD107a." (PMID 35104810, 2022). "However, the combination of systemic IL-2 and autologous tumor vaccination triggered significant therapy-related adverse effects." (PMID 36146527, 2022). "It is possible that Th1 cells provide IL-2 needed to elicit Tc1-mediated anti-tumor immunity." (PMID 35053375, 2022). "We used a modified vaccinia virus in which the interleukin-2 gene was inserted into the thymidine kinase region of the virus and the construct was then injected directly into the tumor providing a source of interleukin-2 inside the tumor without viral replication in normal cells." (PMID 35431929, 2022). "However, the half-life of IL2 in the blood is on the order of minutes, and high-dose infusion regimens are needed to elicit substantial tumor reduction in patients with cancer." (PMID 35235346, 2022). "Both circuits act by the same principle of delivering high levels of IL-2 directly to the tumor." (PMID 36520915, 2022). "Therefore, human peripheral blood mononuclear cells (PBMCs) isolated from the peripheral blood of healthy donors were incubated with TKD/IL-2 to stimulate NK cell reactivity against tumor cells expressing high amounts of mHsp70." (PMID 35720311, 2022). "Macrophages may internalize and secrete TNF- α, NO, IFN-γ, IL-2, IL-6, IL-8, IL-12 and IL-18, so as to play an anti-inflammatory and even anti-tumor role." (PMID 35299759, 2022). "Naturally occurring Tregs are rare, so the presence of Tregs in the TIL populations may be indicative of Tregs in the tumour environment; however, Tregs can also be induced in vitro with Treg-inducing factors, which can include IL2." (PMID 35158816, 2022). "Additional analysis revealed that significant amounts of IL-2 could be produced by tumor-derived CD4+ and CD8+CD45RA- memory T-cells after combined anti-CD3/anti-CD28 stimulation." (PMID 35474089, 2022). "Furthermore, TNFα signaling and IL2/STAT5 signaling pathways were also enriched in FAP+ fibroblastsHighSPP1+ macrophagesHigh tumor samples." (PMID 35365629, 2022). "Interestingly, the addition of IL-2 and IL-15 to the tumor cells contributed to the enhancement of the lysis of tumor cells through increased NK cell activity." (PMID 36010854, 2022). "Thus, OMCPmutIL-2–expanded CD8+ T cells outperformed T cells expanded in IL-2 or IL-15 in multiple murine and human tumor models." (PMID 35603788, 2022).
tumor (continued). "The adoptive transfer of IL-2/PAgs ex vivo expanded Vγ9Vδ2 cells from autologous or allogeneic hosts exhibited potent anti-tumor effects in a variety of cancer patients, such as gastric cancer, osteolytic breast cancer, prostate cancer, and colorectal cancer and so on." (PMID 35747139, 2022). "IL-2/anti-IL-2 complexes, with specificity toward the intermediate- or high-affinity IL-2R, support improved antitumor immunity in comparison to IL-2 when used as a monotherapy or as potentiators of tumor vaccines." (PMID 35651800, 2022). "Size-based entrapment could partially explain why larger IL-2 fusions imparted better tumor growth delay and survival benefit than smaller IL-2 fusions." (PMID 35013154, 2022). "According to another study, residual tumor cells may be removed using mononuclear cells stimulated with IL-2 or cultivated in a serum-free environment." (PMID 36389779, 2022). "Modification of the frequencies of spleen-resident neutrophils, monocytes, macrophages, and tumor-infiltrating Mo-MDSCs were associated with TBI treatment regardless of IL-2 treatment." (PMID 36497152, 2022). "A single intra-tumor administration of the FPC2/IL-2 complex with injectable gel had a favorable effect on the subpopulation ratio of tumor-infiltrating leukocytes as a result of the enhanced expansion of cytotoxic T lymphocytes and decreased number of myeloid subpopulations." (PMID 36233121, 2022). "Cytokines such as IL-2 have long been known as powerful stimulators of anti-tumor immunity." (PMID 36520915, 2022). "Since Lloyd J Old’s original proposal that specific antigens were associated with tumors, the field of cancer immunotherapy has made significant advances to improve efficacy, including the use of high-dose IL-2 therapy, cloning tumor antigens, and identifying tumor-reactive T cells." (PMID 35203357, 2022). "IL-2K35C-moFA was equipotent to human IL-2 wild type (IL-2WT) in activating tumor-killing CD8+ memory effector T cells (CD8+ T) and NK cells bearing the intermediate affinity IL-2 receptors, and less potent than IL-2WT on CTLL-2 cells bearing the high-affinity IL-2 receptors." (PMID 36230665, 2022). "Consequently, the IL-2 anti-tumor effect is usually compromised by the suppressive effect that regulatory cells exert on NK and CD8 T cells." (PMID 36231109, 2022). "Neoadjuvant chemotherapy increased IL-2 production by all tumor-infiltrating T cell subsets." (PMID 36509285, 2022). "Furthermore, activated T cells and macrophages produce IL-10 to enhance the tumor-growing function of IL-2." (PMID 35632758, 2022). "However, LMJ2.5I-IL-2 extended median survival by only 2 days compared to untargeted IL-2, and all mice succumbed to tumor burden." (PMID 36712341, 2022). "We also tested whether FDPS knockdown in addition to NBP treatment could increase the activation and cytolytic activity of Vδ2 T cells and whether this would be enhanced further with concurrent tumor cell expression of IL2." (PMID 36275712, 2022). "In addition, it is known that IL-2 favors the expansion of regulatory T cells that can inhibit the anti-tumor activity of the CAR-T cells." (PMID 36172343, 2022). "Using IL-2, adenoviral gene therapy in prostate cancer patiets was welltolerated; inducing tumor lymphocytic infiltration, increase in IFNγ and IL-4secretion within the tumor, and decrease in prostate specific antigen (PSA)levels." (PMID 36206378, 2022). "For instance, IL-2 is important for activation, differentiation and maintenance of cytotoxic effector cells, such as cytotoxic T cells (CTLs), natural killer (NK) cells and macrophages, but can also directly act on tumor cells by inducing apoptosis." (PMID 36066630, 2022). "In this study, we armed the tumor-selective OVV VVDD with the human IL2 gene." (PMID 35799600, 2022). "We sought to evaluate whether the role of size and binding affinity extends to IL-2 fusion proteins targeting less abundant yet tumor-specific matrix proteins." (PMID 35013154, 2022).
tumor (continued). "However, when impairment of the IL-2 autocrine signaling is compensated for by another costimulatory molecule such as 4-1BB, the CARs accumulate in the bloodstream, suppress tumor growth and resist Tregs-induced immunosuppression." (PMID 35211124, 2022). "Levels of IL-2 were lower in EC patients and slightly elevated after removing the tumor mass." (PMID 36531027, 2022). "In this study, we found that FAVO significantly promoted the expression of tumor IL-2 and IFN-γ, and inhibited the level of IL-6, which may be the mechanisms underlying the antitumor effects of FAVO." (PMID 35392643, 2022). "In addition, the hypoxic acid microenvironment in the local tumor can cause damage to CAR-T cells, in which lactic acid accumulation can inhibit the production of IL-2, thereby affecting the proliferation and function of CAR-T cells." (PMID 36238297, 2022). "The stronger anti-tumor effects observed for Alb-IL2 compared to IL-2 could be attributed to its enhanced half-life which extends contact with IL-2R + lymphocytes, such as T cells, and ultimately potentiates T cell immunity." (PMID 35962391, 2022). "Cryopreserved UCB CAR-T cells were able to recognize and target tumor cells, and they had the capacity to secrete IL-2 (26.0 ± 4.9%) and IFN-γ (19.9 ± 6.7%) in a similar manner to fresh UCB CAR-T (p = 0.63 for IL-2 and IFN-γ expression between fresh and tUCB CAR-T)." (PMID 35804941, 2022). "Eliminating lymphocytes in the tumor microenvironment facilitates infused cells’ trafficking to the tumor site and their accessibility to various homeostatic cytokines, including IL-2, IL-7, and IL-15, while also reducing immunosuppressive cells that impair antigen-presentation." (PMID 35515137, 2022). "IL-2 is therefore honed to tumor tissues to enact its function." (PMID 35104808, 2022). "Strong NK cell induced antitumor immunity was observed, leading to necrosis and decreased tumor cell proliferation without the high rates of toxicity associated with untargeted IL-2 therapy." (PMID 36066630, 2022). "In addition to driving expansion of cytotoxic T cells in these immunologically cold tumors, the synthetic autocrine IL-2 circuit improved the phenotypes of the CAR T cells that infiltrate the tumor." (PMID 36520915, 2022). "Therefore, in our management protocol of HB tumor rupture, peritoneal perfusion with IL-2 was an obligatory procedure to protect patients from peritonitis and peritoneal seeding." (PMID 35391745, 2022). "The synthetic IL-2 circuit was only activated in the targeted double antigen positive tumor, and we observed a significant increase in T cell activation markers in this targeted tumor." (PMID 36520915, 2022). "Furthermore, the splenocytes from T-01-treated mice showed increased secretion of the immune-enhancing cytokines INF-γ, IL-2, and IL-4 and decreased secretion of tumor-suppressive IL-10." (PMID 35615265, 2022). "Subsequently, cytokine secreted from T cells in response to those tumor cells was increased, and those cytokines including IL‐2, IL‐7, IL‐15, and interferon gamma (IFN‐g), could induce PD‐L1 expression." (PMID 34907653, 2022). "A phase I trial for anti‐PSMA CAR T indicated that interleukin‐2 (IL‐2) may play a role in the success of CAR T tumor destruction." (PMID 35844304, 2022). "In vivo, a dose of 3 μg nanobody per gram of body weight in tumor‐bearing mice could attenuate tumor progression and suppress excessive circulating levels of IL‐1a, IL‐2, IL‐10, IL‐12, and IL‐17A pro‐inflammatory cytokines." (PMID 34694686, 2022). "Notably, compared to the sole TBI treatment, the TBI/IL-2 combination significantly decreased tumor-infiltrating DCs, while particularly reducing the population size of the cDC1 subset." (PMID 36497152, 2022). "Feng and Navaratna demonstrated that the initial ratio between regulatory T cells and effector T cells impacts the tumour recurrence time and that the effectiveness of IL-2 use may reverse the immunotherapy outcome." (PMID 35677181, 2022).
tumor (continued). "Moreover, the impact of additional IL-2 supply at the tumor site for T cell stimulation was evaluated." (PMID 35836798, 2022). "Moreover, the tumor specific activation of CAR- or TCR-T cells itself—including high IL-2 secretion—potentially induces the formation of Treg populations." (PMID 35159220, 2022). "Interestingly, using IL-2 or IL-15 cytokines to stimulate NK cells can significantly enhance the anti-tumor ability of their derived EVs." (PMID 35915054, 2022). "Similarly, the human NK cell line NKL expressed HIF-1α upon IL-2 stimulation in hypoxia and exhibited improved anti-tumor cytotoxicity and IFN-γ secretion." (PMID 34999917, 2022). "In tumor models, the cytotoxic activity of NK cells has been shown to be inhibited by the cell–cell interaction with MDSCs (pathogenically activated neutrophils), reducing NK cell activation by IL-2 and perforin production and a significant decline in the ability of NK cells to attack tumor cells." (PMID 35784290, 2022). "Instead, we found that in this fully immunocompetent tumor model, improved CAR T cell-mediated tumor control was only observed with the autocrine configuration of the synthetic IL-2 circuit – i.e. the cytotoxic receptor (CAR) and the synNotch→IL-2 circuit must be encapsulated within the same cell." (PMID 36520915, 2022). "We showed that Treg cells could suppress the proliferation of naive CD4+ T cells and inhibit IL-2 secretion of CD4+ effector cells upon activation by tumor-specific antigens." (PMID 35309296, 2022). "The basis of IL-2 anti-tumor activity is the ability to expand and activate effector T cells." (PMID 35874707, 2022). "Another strategy is to utilize tumor-homing immunocytokines such as interleukin-2 (IL-2)." (PMID 35209102, 2022). "How to target IL-2 to tumor-specific T cells remains a challenge in IL-2 cancer immunotherapy." (PMID 35104810, 2022). "GHCer could be transferred from cancer cells into non-tumor cells located in tumor microenvironment, such as endothelial cells, promoting angiogenesis, as well as into T cells, inhibiting IL-2, interferon-γ, and IL-4 secretion, promoting immunosuppression." (PMID 35158915, 2022). "However, we and others have demonstrated previously that IL-2, when combined with a tumor-targeting antibody, can achieve exposure-dependent tumor control mediated by local stimulation of cytotoxic CD8+ T and NK cells." (PMID 35013154, 2022). "The IL-2 accumulates selectively in the tumor site, boosting the tumor immune response." (PMID 36686835, 2022). "For this particular aim, we used two different strategies: firstly, we addressed activating receptors responsible for NK cell stimulation triggered by an interaction of NK cells with their corresponding tumor antigen TKD in the presence of pro-inflammatory cytokines (IL-2)." (PMID 35720311, 2022). "Similar to the profiles obtained by ELISpot and ELISA, we saw decreased levels of induction of CD54 and MHC-class I on tumor cells by supernatants of patients as compared to those from the healthy individuals when the NK cells were treated with the combination of IL-2 and anti-CD16 mAbs." (PMID 35203349, 2022). "In NSCLC tissues, high expression of NR2F6 was detected in tumor-infiltrating lymphocytes (TILs), and upregulated NR2F6 expression was associated with impaired production of cytokines, including IL-2, TNF-α, and IFN-γ,185 suggesting that NR2F6 on TILs contributes to tumor immunosuppression." (PMID 36123348, 2022). "The results from in vitro experiments showed that T-CD3εζCD28-GFP cells had superior cytotoxic effects on tumor cells in presence of BiTE compared with control T cells, as evidenced by IL-2 and IFN-γ production, T cell proliferation and sequential killing assay." (PMID 36230871, 2022).